GPC3 (glypican 3)
Diseases named in the same sentence as GPC3 in open-access papers (continued):
Sharing a sentence is not in itself a finding about the gene and the disease.
Simpson-Golabi-Behmel syndrome (continued). "GPC3 is responsible for the Simpson-Golabi-Behmel syndrome (SGBS) via the Hedgehog signaling pathway." (PMID 24992906, 2014). "The Simpson-Golabi-Behmel syndrome (SGBS) (OMIM 312870;ORPHA373) is an overgrowth/multiple congenital anomalies syndrome caused by mutations in a semi-dominant X-linked gene encoding Glypican 3 (GPC3)." (PMID 25238977, 2014). "GPC3 can regulate cell proliferation in embryonic mesoderm tissue, as GPC3 gene deletion leads to giant/over growth syndrome, simpson-Golabi-Behmel syndrome (SGBS)." (PMID 34926458, 2021). "In addition, SGBS cells carry an FTO risk allele and the cells do not have a Simpson-Golabi-Behmel syndrome typical mutation in the glypican-3-gene (GPC3) what the name of the cell strain would suggest." (PMID 32466532, 2020).
gastric cancer (31 papers, 2009 to 2025). A primary or metastatic malignant neoplasm involving the stomach. "After identifying these prognostic genes, including CPZ, CTHRC1, DKK1, EGF, and GPC3, we will explore their specific impact on gastric cancer progression, as well as the molecular mechanisms underlying it, particularly the CPZ." (PMID 40296906, 2025). "Equally importantly, levels of GPC3 can potentially be used as a diagnostic marker to define more invasive and aggressive gastric cancers and, therefore, be valuable to assign patients to more tailored treatment regiments." (PMID 27259271, 2016). "In association, a paper recently published identifies GPC3 as a potential metastasis suppressor in gastric cancer." (PMID 27507057, 2016). "Furthermore, we established a novel association between GPC3 expression and cholesterol levels, validating GPC3’s functional role in gastric cancer biology." (PMID 39777330, 2024). "Interestingly, GPC3 was found to be up-regulated in the subgroups of cancer-associated fibroblasts in advanced gastric cancer and correlates with poor patient prognosis." (PMID 39056788, 2024). "In conclusion, our study demonstrated that GPC3 is a target gene of miR-4510, and downregulation of GPC3 could block the metastasis of gastric cancer cells caused by miR-4510 in vivo." (PMID 35050429, 2022). "Additionally, GPC3 is implicated in cellular protection against mitoxantrone in gastric carcinoma cell line PG85-257RNOV, characterized by reduced resistance to mitoxantrone and etoposide by anti-GPC3 ribozyme." (PMID 33791386, 2021). "In conclusion, the loss of GPC3 causes an up-regulation of FoxM1 in gastric cancers." (PMID 27259271, 2016). "Similar oncogenic effects have been reported in other malignancies characterized by elevated GPC3 expression, including ovarian clear cell carcinoma, cervical cancer, lung squamous carcinoma and gastric cancer cells." (PMID 40422229, 2025). "For instance, the down-regulation of GPC3 expression increased the sensitivity of drug-resistant gastric cancer cells to mitoxantrone, and the knockdown of GPC3 increased the sensitivity of ovarian clear cell carcinoma cells to paclitaxel." (PMID 40422229, 2025). "Afterwards, the human GPC3 gene was mapped to the human X chromosome (Xp26), and the first human GPC3 mRNA was cloned from gastric cancer cells in 1997." (PMID 40422229, 2025). "In this study, we confirmed through in vitro cell experiments that cholesterol promotes the expression of GPC3 in gastric cancer cells." (PMID 39777330, 2024). "Recent studies have reported GPC3 as a crucial biomarker and therapeutic target for PD-1 blockade sensitivity in gastric cancer, sparking our interest." (PMID 39777330, 2024). "The results indicated that when GPC3 was overexpressed, the proliferation and migration of gastric cancer cells were significantly enhanced, while downregulation of GPC3 expression reduced the proliferation and migration capabilities of gastric cancer cells." (PMID 39777330, 2024). "The results indicated that GPC3 was highly expressed in gastric cancer tissues with high cholesterol." (PMID 39777330, 2024). "Downregulating GPC3 in GC can inhibit gastric cancer cell metastasis and impact the tumour immune microenvironment." (PMID 37036308, 2023). "Our study confirmed that miR-4510 is inversely correlated with GPC3 in gastric cancer samples and that GPC3 is a direct target gene of miR-4510." (PMID 35050429, 2022). "Glypican-3-expressing gastric cancer (GPC3-GC), characterized as gastric cancer (GC) expressing GPC3, accounts for 11% of the GC cases." (PMID 35050429, 2022). "In gastric cancer, GPC3 is not only highly expressed in the tumor tissue but is also related to its clinical stage, Lauren classification, and prognosis." (PMID 35050429, 2022). "In the end, we screened out 3 molecules, GPC3, GPX3 and PRICKLE1, and constructed a risk scoring model for gastric cancer samples." (PMID 34926458, 2021).
gastric cancer (continued). "A recent study by Yamazawa and colleagues has investigated a panel of stem cell and oncofetal markers including GPC3 in 386 patients with gastric cancer." (PMID 31100935, 2019). "In breast and stomach cancers, the increased expression of IGF1R, GPC3, and IGFBP5 genes is associated with tumor progression and metastasis." (PMID 30944407, 2019). "To further elucidate the decreased expression of eGPC3 in patients with gastric cancer, we sought to compare the expression of GPC3 and CD9 in total serum and corresponding isolated exosomes from five patients with GEA." (PMID 31100935, 2019). "The proteoglycans syndecan-1, syndecan-2, syndecan-4, glypican-1 and glypican-3 were upregulated in gastric cancer with high in vitro and in vivo peritoneal seeding potential, suggesting a role for these molecules in peritoneal dissemination." (PMID 27074785, 2016). "In summary, we have found that GPC3 involved in the metastatic process, and GPC3 repression correlates with poor prognosis for patients with gastric cancer." (PMID 27259271, 2016). "The role of GPC3 in the progression of invasive tumors supports the consideration of drugs that interfere with MAPK/FoxM1 pathways for a subset of gastric cancer patients." (PMID 27259271, 2016). "Together, the preceding observations indicate that the level of GPC3 protein was low in gastric cancer patients' tissues compared to controls." (PMID 27259271, 2016). "To analyze the link between expression level of GPC3 in gastric cancer and patient overall survival, we compared GPC3 levels in 31 patients (Beijing cohort)." (PMID 27259271, 2016). "To examine the expression levels of GPC3 in gastric cancers, we stained 75 gastric tumors (41 adenocarcinomas and 34 signet ring cell carcinomas), 11 adjacent pre-cancerous tissues, and 12 normal gastric tissues with antibodies raised against GPC3 protein." (PMID 27259271, 2016). "Gene expression studies in gastric cancer have shown alterations in the transcription levels of Glypican-3 (GPC3), a member of the glypican family of heparin sulfate proteoglycans." (PMID 27259271, 2016). "In contrast, GPC3 expression is downregulated in lung adenocarcinoma, cell clear renal carcinoma, mesothelioma, ovarian and gastric cancer." (PMID 27507057, 2016). "Recently, glypican 3 (GPC3) has been evaluated as a sensitive marker for AFP-producing gastric carcinoma (GC) and its hepatoid component, and the authors support its usefulness for identifying this aggressive subgroup of GC." (PMID 20062620, 2009). "To investigate whether the expression level of GPC3 in the tumor environment is correlated with cholesterol concentration, we selected two gastric cancer cell lines, HGC-27 and AGS." (PMID 39777330, 2024). "Additionally, we verified that the expression of GPC3 is to some extent dependent on the concentration of cholesterol and identified its function in gastric cancer cells." (PMID 39777330, 2024). "Additionally, we randomly selected gastric cancer tissues from 4 patients in each group and performed Western blotting to validate the protein-level expression of GPC3." (PMID 39777330, 2024). "Consequently, we selected GPC3 for further investigation to explore its role in the development of high cholesterol gastric cancer." (PMID 39777330, 2024). "GPC3 has also been reported for the prognostic diagnosis of gastric cancer." (PMID 36386530, 2022). "miR-4510 may change the immunosuppressive signals in the tumor microenvironment by downregulating GPC3 and inhibiting gastric cancer cell metastasis." (PMID 35050429, 2022). "In another study, overexpression of GPC3 expression could activate Wnt/β-catenin and further promote the proliferation and invasion of gastric cancer cells and reduce the apoptosis of gastric cancer cell lines." (PMID 35050429, 2022). "Therefore, we recommend using sAFP and AFP/GPC3/SALL4 immunohistochemistry for all cases of gastric cancer." (PMID 34706681, 2021).
gastric cancer (continued). "Therefore, we speculated that some miRNAs in GPC3-expressing gastric cancer may also affect the proliferation of gastric cancer by regulating GPC3." (PMID 35050429, 2022). "Besides miR-4510, the expression of GPC3 in gastric cancer is also controversial." (PMID 35050429, 2022). "GPC3, GPX3 and PRICKLE1 were the candidate sites selected in the risk prediction model for OS, which indicated that the genes might have potential roles on the malignant behaviors of gastric cancer." (PMID 34926458, 2021). "Targeting glypican-3 or its downstream signaling pathways, or supplementation with adenoviral overexpression of glypican-3 in such cases might therefore, have the potential to suppress metastasis related to gastric cancer." (PMID 32082161, 2019). "Immunohistochemistry showed serum hepatoid marker alpha-fetoprotein (AFP) and GPC3 positivity in gastric cancer tissues from patients with elevated AFP and GPC3." (PMID 35050429, 2022). "Recently, in addition to AFP, glypican-3 and SALL4 have been considered effective in diagnosing AFP-producing gastric cancer as fetal cancer proteins." (PMID 34792649, 2021). "As a result, the combined expression levels of HSP70 and GPC3 were greater than those of either protein alone in HCC, PDAC, gastric cancer, and CRC." (PMID 32219501, 2020). "Furthermore, in a study of 32 cases of AFP-producing gastric cancer, only 16% were positive for diffuse staining (50% or more of tumor cells) in AFP, whereas it was as high as 56% positive for glypican-3 and 78% for SALL4." (PMID 34792649, 2021). "The most striking finding of our study is the almost complete absence of GPC3 in signet ring cell carcinomas, tumors that histologically more diffuse than other gastric cancer types." (PMID 27259271, 2016). "According to the results presented here, we anticipate that MEK inhibitors may be of value in gastric cancer types where GPC3 is absent." (PMID 27259271, 2016). "In some studies, GPC3 was absent in invasive tumors and metastatic lymph nodes, and the presence of GPC3 causes downregulation of MAPK/FOXM1 (mitogen-activated protein kinase/forkhead box M1) signaling, which reduces the survival rate of gastric cancer patients." (PMID 35050429, 2022). "Among 926 GC cases, 101 (11%) were GPC3‐GC and both diffuse and focal GPC3‐GC showed nodal metastasis more frequently (67% and 55%, respectively) than GPC3‐negative GC (34%), suggesting that GPC3 acts as an oncogene in gastric cancer." (PMID 35050429, 2022). "However the role of GPC3 in gastric cancer is not elucidated and fully understood." (PMID 27259271, 2016). "Moreover, we examined GPC3 and ERBB2 expression levels in gastric cancer (GC)." (PMID 34975912, 2021). "As an oncofetal protein, GPC-3 is primarily present during embryonic period, but absent in normal adult tissues, whereas it’s usually up-regulated in malignant tissues such as HCC (over 80%) and AFP-producing gastric cancer (AFP-GC) (over 90%)." (PMID 34150644, 2021).
lung squamous cell carcinoma (28 papers, 2013 to 2026). "GPC3 has a higher positive rate in lung squamous cell carcinoma, but has a lower positive rate in lung adenocarcinoma 89-91." (PMID 32127929, 2020). "Second, in two established lung squamous cell cancer xenograft models, CARgpc3 T cells almost completely eliminated the growth of gpc3-positive cells." (PMID 29371589, 2018). "High expression of GPC3 was noticed in lung cancer tissues, particularly in lung squamous cell carcinoma." (PMID 28510121, 2017). "GPC3 is also overexpressed in lung squamous cell carcinoma (SCC), but its effects and mechanisms in the progression of lung SCC remain unknown." (PMID 31160489, 2019). "GPC3 may be a promising target for the treatment of lung squamous cell carcinoma." (PMID 34685400, 2021). "Glypican-3 (GPC3) and trophoblast cell-surface antigen 2 (TROP2) are highly expressed antigens in lung squamous cell carcinoma (LUSC) for development of dual-targeted therapy." (PMID 41635855, 2026). "Antibody-based therapies for HCC, lung squamous cell carcinoma (LSCC) and other GPC3-expressed solid tumors are being investigated in preclinical and clinical studies, and several clinical trials using GPC3-targeted CAR-T cells are underway as well." (PMID 38824600, 2024). "Desmocollin-3 was the most specific marker for poorly differentiated squamous cell lung carcinoma (100%), followed by CK5/6 (98.3%), glypican-3 (94.8%), Sox2 (94.8%), S100A2 (81%), S100A7 (75.9%), thrombomodulin (72.4%), p63 (48.3%), and HMCK (36.8%)." (PMID 28510121, 2017). "Next, in two established lung squamous cell carcinoma xenograft models, CAR-GPC3 T-cells almost completely eliminated the proliferation of GPC3-positive cells, indicating that CAR-GPC3 T-cells are capable of detecting lung tumors and efficiently infiltrating cancerous tissues." (PMID 34685400, 2021). "Findings include, first, immunohistochemical assays showed that GPC3 was expressed in 66.3% of lung squamous cell carcinoma samples and 3.3% of lung adenocarcinoma samples, but not in normal lung tissue." (PMID 34685400, 2021). "In terms of findings, firstly, immunohistochemistry assay showed that gpc3 was expressed in 66.3% of lung squamous cell cancer samples and in 3.3% of lung ADC samples but not in normal lung tissues." (PMID 29371589, 2018). "When analyzing only poorly differentiated tumors, HMCK was the most sensitive marker for squamous cell lung carcinoma (100%), followed by p63 (97.8%), CK5/6 (87.0%), Sox2 (71.7%), thrombomodulin (58.7%), desmocollin-3 (52.2%), S100A2 (50%), glypican-3 (45.7%), and S100A7 (45.7%)." (PMID 28510121, 2017).
lung carcinoma (22 papers, 2014 to 2025). "TCGA datasets of all lung cancer samples were chosen to examine mutations and CNAs in the GPC3 and GPC3-related genes." (PMID 34112123, 2021). "Similar effects have been reported for GPC3, -4 and -5 in hepatocellular, pancreatic, and lung cancers." (PMID 32180897, 2020). "In ovarian and lung cancer, GPC3 inhibits the growth of cancer cells by adding 5-aza-2′-deoxycytidine to restore GPC3 expression in cancer cells." (PMID 24992906, 2014). "Currently, reports of GPC3 in lung cancer are limited and ambiguous." (PMID 34112123, 2021). "The importance of GPC3 was furthermore validated in lung cancer cell lines." (PMID 28510121, 2017). "At the same time, we found that GPC3 could be expressed at the plasma membrane in lung cancer cells." (PMID 26684028, 2016). "Current antigen targets in clinical trials for CAR-T cell therapy for lung cancer include MUC-1, CEA, HER2, mesothelin, receptor tyrosine kinase-like orphan receptor 1 (ROR1), glypican-3 (GPC3), EGFR, and PD-1." (PMID 37420216, 2023). "The introduction of the cytoplasmic domain of DAP10 into second-generation CARs M28z and G28z to create M28z10 and G28z10, targeting mesothelin (MSLN) and glypican 3 (GPC3) respectively, resulted in enhanced and prolonged effector function against MSLN+ lung cancer cell lines." (PMID 40612946, 2025). "Glypican-3 (GPC-3) is a heparin sulfate proteoglycan, typically located on the cell membrane of the fetal liver cells, but also expressed in malignant tumors, such as HCC and lung carcinoma." (PMID 39227992, 2024).
yolk sac tumor (21 papers, 2010 to 2025). A non-seminomatous malignant germ cell tumor composed of primitive germ cells. "The three sensitive diagnostic markers for yolk sac tumor are alpha-fetoprotein, glypican-3 and SALL4." (PMID 22978485, 2012). "Immunohistochemical markers for yolk sac tumor (SALL4 or glypican-3) are often seen, corresponding to their yolk sac tumor-like histologies." (PMID 38491228, 2024). "Immunohistochemical markers for yolk sac tumor (SALL4 or glypican-3) decorated 6 cases, corresponding to their yolk sac tumor-like histologies." (PMID 38085333, 2024). "Glypican-3 (GPC3) is an antigen that is highly expressed in yolk sac tumors providing the rationale for peptide-based vaccine therapy in this histologic TGCT subtype." (PMID 38275869, 2024). "It has higher specificity and is more sensitive than α-fetoprotein and glypican-3 for yolk sac tumor types." (PMID 22962582, 2012). "The results exhibited OCT4 and TCL1 are useful diagnostic marker for dysgerminoma, whereas SALL4 is a more sensitive and specific marker for yolk sac tumors than glypican-3." (PMID 22962582, 2012). "SALL4 is also identified as a novel sensitive diagnostic marker for primary germ cell tumors of the central nervous system with high specificity, and is a more sensitive marker than α-fetoprotein and glypican-3 for yolk sac tumors." (PMID 22962582, 2012). "Other recent studies have shown that GPC3 is an immunohistochemical marker for testicular and ovarian germ cell tumors, specifically yolk sac tumor and choriocarcinoma." (PMID 20868507, 2010). "Yolk sac tumors immunohistochemical testing is positive for AFP, glypican-3, SALL4, and placental alkaline phosphatase." (PMID 27144043, 2016). "Many malignant tumors with AFP producing and hepatoid features resembling HCC, such as hepatoid adenocarcinoma of the stomach and primary hepatoid yolk sac tumor (H-YST) of ovary and testis, especially the latter, express AFP, Hep Par 1 and GPC3." (PMID 21443783, 2011). "Therefore, Glypican-3 and AFP were used to check for the presence of yolk sac tumors in the patient’s biopsy." (PMID 36805679, 2023). "Glypican-3 is another new marker with high specificity for yolk sac tumors, and is not expressed in sex cord stromal tumors." (PMID 26742984, 2015). "Glypican hepatoid yolk sac tumor is morphologically and immunohistochemically very similar to HAC, and both can express SALL4, Glypican-3, and AFP, and often do not express somatic cell markers such as CK7 and EMA." (PMID 40740864, 2025).